TTN (titin)
Diseases named in the same sentence as TTN in open-access papers (continued):
Sharing a sentence is not in itself a finding about the gene and the disease.
dilated cardiomyopathy (continued). "We describe a case of concurrent FD, IgAN, and dilated cardiomyopathy-causing mutations in the TTN and BAG3 genes, which has not been reported previously." (PMID 37914990, 2023). "RBM20 and TTN are a pair of genes that are strongly related to dilated cardiomyopathy." (PMID 35207686, 2022). "Here we describe the generation of a mouse model to investigate the underlying disease mechanism of a previously reported titin A178D missense variant identified in a family with non-compaction and dilated cardiomyopathy." (PMID 33637999, 2021). "In addition, both RBM20 and these Titin-derived circRNAs seem to regulate the progression of dilated cardiomyopathy, highlighting the importance of organ-specific biogenesis and function of circRNAs." (PMID 32429565, 2020). "While recent studies detected only mild changes in the expression of circRNAs in hypertrophic and dilated cardiomyopathy compared to healthy controls, often circRNAs of the Titin gene are among those circRNAs that indeed change expression during disease progression." (PMID 32635460, 2020). "Are titin-truncating variants in the TTN gene associated with life-threatening ventricular arrhythmias in patients with nonischemic dilated cardiomyopathy and an implanted cardioverter defibrillator or cardiac resynchronization therapy defibrillator?" (PMID 31251381, 2019). "Also, a study on the expression of cardiac titin in patients with dilated cardiomyopathy reported alterations at the isoform ratio level favouring the more compliant N2BA isoform, with a consequent decrease in passive myocardial stiffness." (PMID 28374191, 2017). "Improved understanding of dilated cardiomyopathy (DCM) due to titin truncation (TTNtv) may help guide patient stratification." (PMID 29073955, 2017). "The most severely affected dilated cardiomyopathy patients harbor Titin truncations in the C-terminal two-thirds of the protein, suggesting that mutation position might influence disease mechanism." (PMID 26473617, 2015). "Additionally, Gaar-Humphreys proposed that the TTN gene could be a crucial factor in the development of dilated cardiomyopathy in dogs, emphasizing its significance as a genetic model for human disease." (PMID 40282318, 2025). "Dilated cardiomyopathy (DCM) is associated with a genetic cause in 20–50% of patients, with the most common pathogenic variants associated with DCM identified in approximately 17% of genotype-positive probands being heterozygous titin truncating variants (TTNtv-s)." (PMID 40022161, 2025). "In subject A, a missense mutation Arg14996Cys, and in subject B, a missense mutation Ile2686Val; however, both variants are categorized as variants of uncertain significance (VUS), and mutations in the TTN gene have been primarily associated with dilated cardiomyopathy, not hypertrophic." (PMID 36426223, 2022). "Moreover, AS of the titin gene has been linked to the regulatory activity of RNA binding motif protein 20 (RBM20), described as a regulator of cardiac AS and whose mutations have been associated with human dilated cardiomyopathy." (PMID 28374191, 2017). "The dilated cardiomyopathy (DCM) pathway involves proteins such as Desmin, DMD, Titin, Tnt, ACTA1, TPM, Laminac, SGCD, TNF-α, IGF-1, TGF-β, and Ang-II." (PMID 32419790, 2020). "In dilated cardiomyopathy (DCM), splicing of Titin (TTN) generates different isoforms, with the shorter, stiffer N2B isoform being optimal for adult heart function, while the longer, more compliant N2BA isoform predominates in fetal hearts and during heart failure." (PMID 40382596, 2025). "There were no TTN-related patients identified possibly because the individuals were in their fertile age, were in their 30s, and did not meet the onset age for dilated cardiomyopathy." (PMID 36072675, 2022).
dilated cardiomyopathy (continued). "Despite that most circular RNAs are generated from constitutive exons in hearts, a critical splicing factor involved in dilated cardiomyopathy (i.e., RBM20) specifically regulates the generation of ecircRNAs from skipped exons corresponding to the I-band region of the Titin gene." (PMID 32429565, 2020). "However, the role of IER3 in heart failure, and particularly in titin-based dilated cardiomyopathy, has not been investigated so far." (PMID 28353642, 2017). "TTN mutations, whether recessive or dominant, are also emerging as major causes of dilated cardiomyopathy and have been implicated in hypertrophic cardiomyopathy (HCM), however no families with co-segregation of TTN missense variants with HCM or DCM have been identified to date." (PMID 33449170, 2021).
heart failure (91 papers, 2014 to 2026). Inability of the heart to pump blood at an adequate rate to meet tissue metabolic requirements. "Is it inevitable that all patients with TTN mutations will experience cardiac changes leading to heart failure, or is a second “hit” from environmental, genetic, or epigenetic factors always required for this progression?" (PMID 41190030, 2025). "Altered titin stiffness has been linked to heart failure with preserved ejection fraction (HFpEF), where increased longitudinal passive stiffness is attributed to changes in post-translational modifications of titin." (PMID 40512239, 2025). "Heterozygous truncating variants in the sarcomere protein titin (TTN) are the most common genetic cause of heart failure." (PMID 39688912, 2024). "Regarding mortality, two patients died during follow-up due to refractory heart failure, both of whom had titin mutations." (PMID 38999368, 2024). "The frequent titin (TTN) pathogenic findings reflect the known high frequency in familiar heart failure and its arrhythmogenic potential and highly correlate with the autopsy findings." (PMID 37178278, 2023). "Altered titin N2BA/N2B expression ratio is associated with certain forms of heart failure (HF) in humans." (PMID 35575093, 2022). "As shown here, RBM20 and SLM2 share several of their targets in the heart, including TTN, which are important parts of the heart failure phenotype observed in humans with mutated RBM20." (PMID 34273561, 2022). "The genetic screening study witnessed mutations in TTN, encoding the myofilament titin responsible for the occurrence of heart failure." (PMID 34681194, 2021). "Modifications of titin, which change protein length, and relative stiffness affect resting tension of the ventricle and are associated with acquired forms of heart failure." (PMID 32859027, 2020). "Heart failure is a common clinical syndrome often caused by abnormalities within sarcomeric proteins including the giant, spring like protein titin." (PMID 32859027, 2020). "In heart failure, changes in contributors to the passive properties of the ventricle, such as titin and collagen, and loss of the metabolic enzyme creatine kinase, increase resistance to filling resulting in diastolic dysfunction." (PMID 29193283, 2018). "Transferase dUTP nick end labeling (TUNEL) and ssDNA stainings showed induction of apoptosis in titin-deficient cardiomyocytes during heart failure development, while IER3 response was dysregulated." (PMID 28353642, 2017). "Missense single-nucleotide polymorphisms (mSNPs) in titin are emerging as a main causative factor of heart failure." (PMID 27683155, 2016). "Mutations in TTN can lead to a decrease in titin expression or to the formation of abnormal titin proteins, which can affect the elasticity of the heart muscle and lead to its dilation and subsequent heart failure." (PMID 37222281, 2023). "Recent studies suggest that TTN variants may also act as genetic modifiers that predispose to heart failure in other conditions like myocarditis." (PMID 37477868, 2023). "Furthermore, a mouse model with TTN mutations only developed heart failure if they were also treated with anthracyclines while wild type mice treated with the same dose did not develop heart failure." (PMID 33517910, 2021). "In addition, patients who develop heart failure related to other causes have significant changes to titin at the transcriptional and post translational level." (PMID 32859027, 2020). "In addition to genetic and transcriptional modifications, post-translational modifications of titin also play an important role in cardiac physiology and changes associated with heart failure." (PMID 32859027, 2020). "Its expression is blunted during heart failure development in a titin-deficient mouse model." (PMID 28353642, 2017). "Mutations in TTN have been shown to cause heart failure in humans." (PMID 27877193, 2016).
heart failure (continued). "Knocking out the α-MHC K1897 in mice results in impaired interaction between α-MHC and Titin, leading to heart failure." (PMID 40584617, 2025). "On the other hand, increasing lactate levels by administering sodium lactate or inhibiting key lactate transporters in cardiomyocytes enhances K1897 Kla and strengthens the α-MHC-titin interaction, improving heart failure outcomes." (PMID 39897556, 2025). "This opens up a promising avenue for therapeutic intervention by designing ASOs that specifically target the RBM20 binding sites on TTN pre-mRNA to reduce diastolic stiffness in patients with heart failure with HFpEF and DCM." (PMID 41190030, 2025). "Modulating RBM20 activity to regulate titin isoform expression is currently being explored to alleviate elevated myocardial stiffness in heart failure with preserved ejection fraction (HFpEF)." (PMID 40119572, 2025). "More specifically, 37.5% of the myasthenic patients with anti-striational antibodies (anti-titin, anti-ryanodine, and anti-Kv 1.4) develop myocarditis, which manifests as cardiac failure and/or arrythmias at 13 to 211 months from MG onset." (PMID 38673546, 2024). "So far the team has reported the treatment of Hodgkin's lymphoma (HL) in pediatric patients with titin (TTN) gene mutation and heart failure." (PMID 38547930, 2024). "We identified highly conserved sequences (denoted E1) that regulate the transcription of TTN, an essential CM gene that harbors pathogenic variants in patients with DCM and heart failure." (PMID 39688912, 2024). "Correspondingly, compared with LDHA-cWT mice, LDHA-cKO mice showed a weaker α-MHC–Titin interaction, which was significantly decreased in Ang II-induced heart failure." (PMID 37443257, 2023). "To analyze the effects of p300 on α-MHC K1897 lactylation and α-MHC–Titin interaction in Ang II-induced heart failure, we used p300 inhibitor or p300 activator in vitro and in vivo." (PMID 37443257, 2023). "In conclusion, α-MHC K1897 lactylation regulates the interaction between α-MHC and Titin, and the decrease in α-MHC K1897 lactylation predisposes to heart failure." (PMID 37443257, 2023). "By contrast, upregulation of the lactate concentration by administering sodium lactate or inhibiting the pivotal lactate transporter in cardiomyocytes can promote α-MHC K1897 lactylation and α-MHC–Titin interaction, thereby alleviating heart failure." (PMID 37443257, 2023). "Surprisingly, we found that under baseline conditions and Ang II-induced heart failure, treatment with NALA caused significant increase in α-MHC K1897 lactylation and α-MHC–Titin interaction." (PMID 37443257, 2023). "α-MHC K1897R KI mice that fail to undergo lactylation have a reduced interaction between α-MHC and Titin, which disturbs myofibrillar arrangement and impairs cardiac function, and in turn aggravates heart failure." (PMID 37443257, 2023). "Our results show that intervention with the p300 acyltransferase activator failed to fully rescue α-MHC K1897 lactylation, as well as α-MHC–Titin interaction in Ang II-induced heart failure mouse model." (PMID 37443257, 2023). "α-MHC K1897R knock-in (KI) mice exhibit impaired α-MHC–Titin interaction and develop aggravated heart failure." (PMID 37443257, 2023). "Decreasing lactate production by chemical or genetic manipulation reduces α-MHC lactylation, impairs α-MHC–Titin interaction and worsens heart failure." (PMID 37443257, 2023). "Consequently, titin stiffening could thus contribute to the alterations in myocardial mechanic alterations associated with oxidative stress, which often accompanies aging or heart failure." (PMID 35047109, 2022). "Better understanding the mechanisms involved in titin isoforms transition shows a silver lining for treating heart failure with myocardial wall stiffness." (PMID 35783855, 2022).
heart failure (continued). "Overall, posttranslational modifications alter titin-based myocardial passive stiffness representing an attractive target for therapeutic treatment in common forms of heart failure, especially heart failure with preserved ejection fraction." (PMID 35047109, 2022). "Oxidative modification of sarcomere proteins and especially titin has been reported for several conditions like ischemia/reperfusion, in heart failure or muscular dystrophies." (PMID 35846001, 2022). "MMP-2 also destroys other contractile proteins, particularly MLC2, troponin I (TnI), and titin in the ischemic myocardium, which can lead to disorders in myocardial contractility and heart failure." (PMID 35330470, 2022). "In summary, our findings suggest that even though titin size switching occurs and myocardial stiffness is changed at younger age of Rbm20 KO rats, the overt phenotype of heart failure exhibits at older age." (PMID 34523260, 2021). "High sarcomere passive stiffness due to low PKG titin phosphorylation is found in some patients with heart failure." (PMID 34745372, 2021). "As previously demonstrated by multiple studies, PKG-dependent hypo-phosphorylation of titin contributes to the increased stiffness that is observed in heart failure." (PMID 34356367, 2021). "Emphasis is on how modification of titin can be utilized as a therapeutic target for treatment of heart failure." (PMID 32859027, 2020). "Our study paves the way for interventions that target the stiffness of titin in common forms of heart failure, particularly heart failure with preserved ejection fraction (HFpEF)." (PMID 32929035, 2020). "Although increasing levels of cGMP is likely to have many effects for improving heart failure, the effects on phosphorylation of the titin N2Bus element is likely to be significant." (PMID 32859027, 2020). "We also include a detailed coverage of the complex changes in phosphorylation at specific titin residues, which have been reported in both animal models of heart disease and in human heart failure, and their correlation with titin‐based stiffness alterations." (PMID 30989819, 2019). "Knowledge of the relationship between titin PTMs and titin elasticity can be exploited in the search for therapeutic approaches aimed at softening the pathologically stiffened myocardium in heart failure patients." (PMID 30989819, 2019). "Altered splicing of TTN occurs in a number of cardiac diseases such as heart failure, ischemic heart disease, and hypertrophic cardiomyopathy." (PMID 30051286, 2018). "Reversing the induction of PP5 in heart failure would promote titin phosphorylation and help reduce pathologically increased diastolic stiffness." (PMID 29343782, 2018). "Patients experiencing heart failure with preserved ejection fraction exhibit Titin hypophosphorylation, which increases the resting tension of cardiomyocytes and impairs diastolic function." (PMID 28328397, 2017). "To investigate the role of IER3 signaling in heart failure, we analyzed IER3 expression during DCM development in heterozygous titin-deficient mice." (PMID 28353642, 2017). "A comprehensive overview is provided of studies that have measured altered titin phosphorylation and titin-based passive tension in myocardial samples from human heart failure patients and animal models of heart disease." (PMID 28510118, 2017). "Future studies should explore how important this oxidative modification of titin is in the context of heart failure or muscle disease and to what degree it affects titin-based passive stiffness in vivo." (PMID 25373878, 2015). "Reduced contractile function due to morphological alterations in cytoskeletal proteins such as actin and titin have been reported in studies on heart failure." (PMID 24587307, 2014). "Moreover, lactylation of Snail1 mediates the endothelial-to-esenchymal transition after MI, while α-MHC lactylation maintains the α-MHC–Titin interaction to alleviate the development of heart failure." (PMID 38421727, 2024).